TNF (tumor necrosis factor)
Diseases named in the same sentence as TNF in open-access papers (continued):
Sharing a sentence is not in itself a finding about the gene and the disease.
epilepsy (continued). "Pro-inflammatory cytokines, such as tumor-necrosis factor (TNFα) and interleukin-6 (IL-6), were increased in epilepsy patients and epilepsy models." (PMID 29566716, 2018). "Neuroinflammatory processes have been repeatedly shown to be activated in both experimental and human epilepsy, including the release of cytokines such as Il-1β and TNF-α." (PMID 30237424, 2018). "Prior studies demonstrate that elevated levels of interleukin-1β (IL-1β), interleukin-6 (IL-6), interleukin-8 (IL-8), and tumor necrosis factor (TNF) are linked to neuronal hyperexcitability and are found in serum and CSF of patients with epilepsy." (PMID 30344507, 2018). "α-Asarone decreased TNF-α, IL-1β in the rat epilepsy model as well as in activated primary cultured microglia." (PMID 29312110, 2017). "Activated microglia is a prominent source of proinflammatory factors such as TNF-α, IL-1β, both of which are neurotoxic and proved to promote hyperexcitability in epilepsy." (PMID 29312110, 2017). "Release of pro-inflammatory cytokines, such as interleukin-1ß (IL-1β) and tumor necrosis factor-alpha (TNFα) increases both in experimental models of epilepsy and in patients." (PMID 28210205, 2017). "There are few clinical studies on the TNF system and its effects on epilepsy in spite of intense investigation in animals." (PMID 27006531, 2016). "For example, a recent study found that vagus nerve-stimulation (VNS) in epilepsy patients inhibits peripheral blood production of TNF, IL-1β, and IL-627." (PMID 27761024, 2016). "For epilepsy and bipolar disorder, overlapping results regarding the cytokine system have been reported, namely, alterations of IL-1β, IL-2, IL-4, IL-6, and TNF-α." (PMID 24757498, 2014). "In epilepsy, the pleiotropic cytokine TNF is indicated as being an important effector/mediator of neuroinflammation and cell death." (PMID 23634661, 2013). "In rat model of KA-induced epilepsy, injury in hippocampus occurs accompanied by upregulation of cytokines including TNF-α and IL-1 in glial cells." (PMID 21949812, 2011). "Prolonged expression of reactive microglia in KA-induced epilepsy contributes to the production of proinflammatory cytokines such as tumor necrosis factor alpha (TNF-α), interleukin-1β, and interleukin-6 resulting in neuronal loss and the promotion of epileptic seizures." (PMID 41233341, 2025). "TNF concentrations might rise further during the progression of epilepsy in DT‐treated CCL17DTR mice, for example, during the peak of SGS activity, and may impair GJ coupling and K+ buffering at later time points." (PMID 39607395, 2025). "In addition, it has been shown that VU0360172, a mGlu5 PAM, can reduce seizures in virus-induced epilepsy model mice and also reduce IL-6 and TNF-α production." (PMID 39858450, 2025). "A significant increase in proinflammatory cytokines, including IFN-γ, IL-1β, IL-6, IL-10, IL-12, and TNFα, was observed after epileptogenesis, and levels of these inflammatory factors may serve as biomarkers for epilepsy." (PMID 39249163, 2024). "Furthermore, some inflammatory mediators, such as TNF‐α, IL‐1β, and IL‐6, play a significant role in the development of epilepsy, and Crocin presents an inhibitory effect on these inflammatory cytokines." (PMID 38775292, 2024). "Moreover, a study reveals neutrophils and TNFα as central regulators of neuronal hyperexcitability of diverse etiology in human epilepsy." (PMID 38020614, 2023). "Moreover, miR-27a-3p effectively promotes pathways to increase the expression levels of interleukin-1β (IL-1β), IL-6, and tumor necrosis factor-α (TNF-α) in the hippocampus of rat model of epilepsy." (PMID 37727513, 2023). "ALC administration has been shown to decrease TNF activation in an epilepsy model." (PMID 37745053, 2023). "TNF-α is released from activated microglia and astrocytes, and it can induce epilepsy." (PMID 37239204, 2023).
epilepsy (continued). "Overall, these findings suggest that myricitrin’s antioxidant and TNF-α-mediated anti-inflammatory potential may help to alleviate seizures in epilepsy." (PMID 36672083, 2023). "Targeting to cut off the purine metabolism of TNF-α and microglia may be a new strategy for the treatment of epilepsy." (PMID 38074156, 2023). "Previous studies demonstrated that different inflammatory mediators, including tumor necrosis factor (TNF)-α, IL-1β, and IL-6, may contribute to epilepsy development and progression." (PMID 35647304, 2022). "To date, modulation of neuroinflammation by the GM through uncontrolled activation of Th-17, production of IL-1-b, IL-6, and TNF-α, as well as a reduction of SCFAs that result in BBB alterations, are the only known causal interactions that determine the onset of epilepsy." (PMID 36138769, 2022). "O. limbata could exert a neuroprotective effect by reducing oxidative stress induced by ROS and by downregulating the overexpression of inflammatory cytokines p-NFkB and TNF-α in epilepsy." (PMID 35392411, 2022). "We speculate that crocin may inhibit the inflammatory response through reducing the content of the pro-inflammatory cytokine TNF-α in the hippocampal region, thus achieving the effect of suppressing epilepsy." (PMID 35431921, 2022). "This could be possible through the downregulation of epilepsy-induced raised levels of NF-κB and TNF-α." (PMID 33920713, 2021). "Since TNF signaling may have an important role not only in ictogenesis, but also in early phases of epileptogenesis, anti-TNF-α therapy for epilepsy is also under debate due to the suspected risks of demyelination, infection, and cancer development." (PMID 34446808, 2021). "In epilepsy models, meloxicam diminished IL-1β and TNF-α levels." (PMID 34573138, 2021). "It is speculated that epilepsy-driven inflammations may attack circadian clock because inflammatory cytokines (e.g., TNF-α and IL-1β) are modifiers of clock genes, such as Rev-erbα and Per225–27." (PMID 33619249, 2021). "Trans-caryophyllene (TC) applied in epilepsy may be attributed to its ability to reduce the expression of pro-inflammatory cytokines, such as TNF-α and IL-1β." (PMID 33746751, 2021). "Furthermore, resident glial cells are rapidly activated and trigger the release of proinflammatory cytokines such as interleukin-1 (IL-1β), tumor necrotic factor-alpha (TNF-α), and interleukin-6 (IL-6), which clinically compromise the prognosis of epilepsy." (PMID 34422216, 2021). "In rodent models of KA- or PTZ-induced epilepsy, increased levels of seizure behavior, microglial activation markers (Iba-1, TNF-α, IL-1β, IL-6, iNOS, and COX-2), NF-κB activation, apoptosis-related proteins (Bax and caspase-3/8/9) and ROS were confirmed in the hippocampus." (PMID 34680566, 2021). "The content of TNF-α in brain tissue of epilepsy rats similarly shows a significant upward trend." (PMID 33959658, 2021). "TNF-alpha (TNFα) is a proinflammatory cytokine that has been shown to regulate synaptic activity in the hippocampus through control of astrocyte glutamate release, and is also upregulated in epilepsy." (PMID 34658792, 2021). "Interestingly, invasive electrical stimulation of other brain regions also attenuates neuroinflammation: high-frequency deep brain stimulation (DBS) (130 Hz) of the anterior thalamic nucleus resulted in a decrease of TNF-α and IL-1β in a rat model of epilepsy." (PMID 33514001, 2021). "The reduced expression of NF-κB and TNF-α in PTZ induced animal model of epilepsy shows that the antiepileptic potential of fruit of Rosa webbiana may be the outcome of the attenuation of NF-κB and TNF-α." (PMID 33920713, 2021). "Furthermore, the exosomes significantly inhibited the release of TNF‐α and IL‐1β, and cytokine release was further decreased by circHivep2+ exosomes in the hippocampus at 72 hours after KA‐induced epilepsy." (PMID 33002329, 2020).
epilepsy (continued). "Moreover, after tonic–clonic seizures, in vivo studies indicated an elevated production and secretion of proinflammatory cytokines like IL-1β, IL-6, and TNF-α in cerebral spinal fluid (CSF) and blood serum in patients with epilepsy." (PMID 30922332, 2019). "The serum and gene expression of the inflammatory cytokines—IL-1α, IL-1β, IL-2, IL-6, IL-8 and TNF-α—showed the highest levels among the “Epilepsy-only” group followed by lower levels in the epilepsy–cannabis users and finally the lowest levels in the healthy controls." (PMID 31757102, 2019). "TNF-α is expressed at a high level during epilepsy, and the specific mechanism of its action in epilepsy may be related to glial cells." (PMID 31049031, 2019). "Investigation on post-surgery patients with intractable epilepsy revealed increased levels of HMGB1, TLR4, RAGE, NF-κB, p65 and inducible nitric oxide synthase (iNOS) in the brain of the epilepsy group as well as increased levels of IL-1, IL-6, TNF-α, TGF-β, and IL-10 in epilepsy patients." (PMID 30271319, 2018). "Although TNF-α may have an important role in epileptogenesis, anti-TNF-α therapy for epilepsy is under debate due to the suspected risks of infection and cancer development." (PMID 29764485, 2018). "The α-asarone role in the mitigation of the learning and memory deficits as induced by epilepsy, as presented in our study, might be explained by the α-asarone effects on IL-1β and TNF-α production." (PMID 29312110, 2017). "Previous research has reported that seizure induces the generation of cytokines, such as interleukin (IL)-1β, IL-6, and tumor necrosis factor (TNF)-α, and that the interactions among these cytokines are related to the development of epilepsy and play a crucial role in epileptogenesis." (PMID 24381640, 2013). "Therefore, in the present study, we investigated the roles of TNF-α in vasogenic edema and its related events in rat epilepsy models provoked by pilocarpine-induced SE." (PMID 22240205, 2012). "In a variety of animal models of epilepsy, as well as in patients suffering from epilepsy, increased elevations of pro-inflammatory cytokines IL-6, IL-1β and TNF-α have also been found in the cerebrospinal fluid, and many of these cytokines have been shown to have proconvulsant activity." (PMID 20067608, 2010). "Interestingly, TNF-α exerts dose-dependent biphasic effect on epilepsy." (PMID 41306289, 2025). "For instance, a rapid activation of proinflammatory cytokines such as IL-1β, IL-6 and TNF-α was observed both in animal models of acquired epilepsy and in brain tissue obtained from patients with temporal lobe epilepsy or cortical developmental malformations undergoing epilepsy surgery." (PMID 39239395, 2024). "However, there is a paucity of literature reporting the use of anti-TNF agents in epilepsy." (PMID 39765588, 2024). "However, this concept cannot be expanded to all epilepsies; using a rat model of audiogenic seizures, de Deus and colleagues reported similar levels of IL-6, IL-10, TNF-α and IL-1β between controls and experimental animals, but high correlation between seizure severity and nitrate levels." (PMID 35052661, 2022). "In addition, glucocorticoid therapy has achieved the prevention and treatment of epilepsy and epileptic encephalopathy by directly inhibiting the expression and release of IL‐1β and TNF‐α,12, 13 but has serious side effects (such as hypertension and osteoporosis)." (PMID 36301030, 2022). "Additionally, there is in vitro and in vivo evidence that vitamin E can reduce neuroinflammatory responses mediated by microglial cells, including studies showing that treatment with alpha-tocopherol lowered hippocampal levels of IL-1β and TNF-α in an animal model of epilepsy." (PMID 34630015, 2021). "This coupling may be used as a strategy to treat epilepsy by inhibiting TNFα signaling." (PMID 35069411, 2021). "In addition, elevated level of TNF-α is revealed in mice models for epilepsy." (PMID 32403392, 2020).
epilepsy (continued). "The brain tissue of patients with epilepsy undergoing surgical resection exhibits a strong inflammatory response, including reactive astrocyte proliferation, the infiltration of activated microglia, and the upregulation of various pro-inflammatory factors, including Cox-2, IL- 1β, TNF-α, and IL-6." (PMID 30983975, 2019). "However, it remains unclear whether cytokine-related pathways, particularly TNFα signaling, have a critical role in the development of epilepsy." (PMID 29464573, 2018). "Proinflammatory cytokines such as IL-1β, TNF-α and IL-6 have been shown to be overexpressed in experimental models of seizures, prominently by glia, suggesting that glia activation may contribute to vascular inflammation in epilepsy." (PMID 20863362, 2010). "PCR results show the expression of IER3, TNF, GPANK1, and ATF6B in hippocampus of epilepsy model largely consistent with bioinformatics predictions." (PMID 41466027, 2026). "Blood and brain tissues were collected for biochemical assays (SUR1, TRPM4, IL-1β, IL-6, TNF-α, TAS, TOS, OSI, thiol-disulfide homeostasis), histological analyses (H&E, Cresyl Violet, and 8-OHdG immunostaining), and qRT-PCR of epilepsy-related miRNAs." (PMID 41718951, 2026). "In our research on epilepsy development, we concentrated on how EGCG influences the expression of inflammatory proteins TNF‐α and IL‐1β." (PMID 41523603, 2025). "Elevated levels of systemic inflammatory biomarkers, including interleukins (ILs), tumor necrosis factor (TNF), interferon (IFN), and procalcitonin (PCT), have been identified in patients with epilepsy." (PMID 40520617, 2025). "Cytokine and chemokine profiles in children with FIRES show an elevation of Th1 specific cytokines (IL-2, TNF, INF-γ) and chemokines when compared to children with other forms of epilepsy or encephalopathy." (PMID 40310164, 2025). "We performed Western blot analysis to measure TLR2, TLR4, NF-κB, and TNF-α protein levels in primary human cells derived from fresh surgically resected tissue samples of patients with HGG, LGG, and epilepsy." (PMID 40809181, 2025). "In this study, immunohistochemical analysis revealed a significant downregulation of Nrf2, alongside elevated TNF-α expression in the cerebral cortex and hippocampus of PTZ-challenged mice, consistent with previous studies using epilepsy animal models." (PMID 41405779, 2025). "Serum levels of 5 cytokines related to neuroinflammation in epilepsy patients (IL1b, IL4, IL6, IL10, and TNF‐alpha) were measured using SIMOA, an ultrasensitive ELISA technique for analyzing molecules in biological samples." (PMID 40542608, 2025). "Primary outcome measures included epilepsy latency, Morris water maze escape latency, oxidative stress markers (MDA, GSH, SOD), inflammatory factors (IL-1β, TNF-α), and Glial fibrillary acidic protein (GFAP)." (PMID 40709096, 2025). "Interleukin-1β (IL-1β) and tumor necrosis factor α (TNF-α) are important pro-inflammatory cytokines, which are considered to be the among the main cytokines involved in the pathogenesis of epilepsy." (PMID 41154178, 2025). "Even in epilepsy, HS is the main pathology of cognitive and functional disorders that are specifically related to TLE, releasingIL-1b, TNF, and IL-6." (PMID 39166055, 2024). "Novel therapeutic targets of epilepsy include interleukin (IL)-1β, cyclooxygenase (COX), tumor necrosis factor (TNF), and IL-6 receptor." (PMID 39723425, 2024). "Elevated levels of tumor necrosis factor-α (TNF-α) have been observed in the brains of patients with both AD and epilepsy." (PMID 38999445, 2024). "The role of other biologic agents, including the anti- TNF- α Etanercept and the anti-CD20 antibody Rituximab, is limited to patients with specific etiologies of epilepsy and SE." (PMID 38078329, 2023).
epilepsy (continued). "Logistic regression models demonstrated that the probability of FE can be evaluated using GDNF in LF and BDNF in BS; that of MDD using GDNF in LF and cortisol and TNF-α in BS; and that of epilepsy with MDD using GDNF in LF and TNF-α and BDNF in BS." (PMID 38069144, 2023). "Proinflammatory factors in the brain, such as interleukin-1β (Il-1β), Il-6, and tumor necrosis factor (TNF-α), initiate downstream inflammatory cascades and lead to impairment of neuronal function, which promotes the occurrence and development of epilepsy." (PMID 37365625, 2023). "In murine models of inflammation, LTG significantly inhibited IL-1β, IL-6, and TNF-α secretion in vivo and in vitro, revealing possible immunomodulatory properties of LTG in epilepsy and BD." (PMID 34791253, 2022). "In the present study, TNF-α, IFN-γ and IL-6 levels increased in the epilepsy models, while IL-10 and TGF-β2 levels decreased, and these effects were reversed by HsTx2 treatment." (PMID 36457055, 2022). "Previous findings provide strong support for the involvement of pro-inflammatory cytokines in the pathophysiology of epilepsy with elevated levels of the pro-inflammatory cytokines IL-1β, IL-6, IL-10, IL-17, IFN-α, and TNF-α." (PMID 34791253, 2022). "Inflammatory mediators (e.g., Interleukin (IL)-1β, Tumor necrosis factor (TNF)-α) have been found increased in the brain following seizures and during epilepsy in both experimental models of epilepsy and patients." (PMID 34572093, 2021). "LncRNA UCA1 was downregulated in epilepsy, whereas the UCA1/miR-203/MEF2C axis inhibited the activation of NF-κB signaling pathway and IL-6, TNF-α, and Cox-2 levels in epilepsy." (PMID 33776905, 2021). "Tumor necrosis factor (TNF) has multiple subtypes, among which TNF-α is the most highly correlated to epilepsy." (PMID 33959658, 2021). "Microglia activation not only increases the levels of brain inflammatory factors and TNF-α but also enhances the activities of induced nitric oxide synthase (iNOS) and cyclocycox-2 (COX-2), which can enhance the induction of epilepsy induced by neurogenesis." (PMID 33746751, 2021). "Indeed, gliosis, microglia activation, and cytokine production, such as interleukin (IL)-1β and tumor necrosis factor (TNF)-α, and consequently neuroinflammation can change neuronal excitability by modulating receptor function and expression, perpetuating the chronic nature of epilepsy." (PMID 33331416, 2020). "The contents of IL-6 and TNF-α in serum of EP + miR-103a inhibitors group was significantly lower than that in the EP + inhibitors NC group (P < 0.05), indicating that the interference of miR-103a expression could reduce the inflammatory damage in epilepsy rats." (PMID 31049031, 2019). "In the context of epilepsy, MAPK are thought to play a role in Cx43 phosphorylation, involving TNF-α, interleukin (IL)-1b and VEGF." (PMID 31887157, 2019). "In the context of epilepsy, microglia and astrocyte activation is routinely observed in the epileptic brain foci from patients, alongside elevated levels of CX3CR1, IL-6 and TNF-α." (PMID 31717556, 2019). "In an experimental model of epilepsy, deletion of TLR3 limits seizures, reduces levels of cytokines TNF-α and IL-1β, decreases levels of microglial activity, and increases survival rates." (PMID 29764485, 2018). "Serum IL-6, IL-1β, TNF-α, and MIP-1α levels were elevated in AED-resistant epilepsy patients and, in patients undergoing resection of the epileptogenic region, IL-1β, TNF-α, and MIP-1α levels decreased after 8 weeks postoperatively." (PMID 27737716, 2016). "Several other mechanisms including TNF-α and Toll-like receptor (TLR) signalling have been described in epilepsy." (PMID 25078263, 2015). "TNF-α is rapidly upregulated in the CNS by seizures, and intrahippocampal injection of TNF-α potently inhibit seizure in a mice model of epilepsy." (PMID 21989210, 2011).